CD46 (CD46 molecule)
Diseases named in the same sentence as CD46 in open-access papers (continued):
Sharing a sentence is not in itself a finding about the gene and the disease.
metastatic prostate carcinoma (1 paper, 2024). A carcinoma that arises from the prostate gland and has spread to other anatomic sites. "This agent has also been used for the clinical treatment of metastatic prostate cancer by targeting CD46 (NCT03575819)." (PMID 38919630, 2024).
myocardial inflammation (1 paper, 2024). "We hypothesize that both CD46 and CD59 shedding and the potent cytokine and chemokine release into the circulation are simultaneously involved in the acute phase of the post-ischemic immune response and myocardial inflammation." (PMID 39523332, 2024).
Neisseria gonorrhoeae infection (1 paper, 2014). "During Neisseria gonorrhoeae infection, bacterial pili initiate signaling pathways via CD46 that recruit cortical plaques directly to the adherent bacteria." (PMID 25470779, 2014).
Nephropathy (1 paper, 2011). A nonspecific term referring to disease or damage of the kidneys. "Previously, mutations in complement factor H, CD46 (membrane cofactor protein) and factor I were identified among patients with biopsy-proven C3GN, but CFHR5 nephropathy is the first description of C3GN associated with a mutation in the CFHR5 gene." (PMID 21114651, 2011).
Pleural effusion (1 paper, 2023). The presence of an excessive amount of fluid in the pleural cavity. "The expression levels of soluble CD46 (sCD46), soluble CD55 (sCD55), and soluble CD59 (sCD59) in pleural effusion were quantified by enzyme-linked immunosorbent assay, and the receiver operating characteristic (ROC) curves were plotted to evaluate the diagnostic and co-diagnostic values." (PMID 36820087, 2023).
protein deficiency (1 paper, 2020). "Severe CD46 protein deficiency was also reported in a patient with aHUS and his healthy sister, both of whom were homozygous for another RV, CD46 c.286+1T>G, affecting the same splice site." (PMID 33224962, 2020).
renal clear cell carcinoma (1 paper, 2021). "The histological findings of C3d and C5b-9 on renal tumor cells led to the hypothesis that the complement system could be involved in the immune response against ccRCC expression level and cellular distribution of CD46, CD55, and CD59 on renal clear cell carcinoma cells." (PMID 34572075, 2021).
renal tumor (1 paper, 2019). "In addition, CD46 also seems to be a connection point of the innate and adaptive immune system, and itself is also regulated by various inflammatory cytokines like IL-1beta, IL-4, and TGF-β, which downregulate CD46 expression in RPTECs and renal tumor cell lines." (PMID 30958843, 2019).
retinal degeneration (1 paper, 2018). Degeneration of the retina. "Outer retinal degeneration resembling retinal changes seen in AMD was observed in 10-month-old mice lacking CD46, which is thought to regulate the aggregation of C3b and C4." (PMID 29497373, 2018).
small vessel stroke (1 paper, 2017). "Hence, the up-regulation of CD46 mRNA found in patients with large artery and small vessel stroke is entirely in agreement with current evidence, signifying the crucial role that CD46 plays in the pathogenesis of large artery and small vessel stroke." (PMID 28199366, 2017).
squamous cell cervical cancer (1 paper, 2020). "We carried out a multivariate Cox regression analysis and developed six ARG-related prognostic signature for the survival prediction of patients with squamous cell cervical cancer (Risk score = − 0.63*ATG3–0.42*BCL2 + 0.85*CD46–0.38*IFNG+ 0.23*NAMPT+ 0.82*TM9SF1)." (PMID 33160404, 2020). "Next, we carried out multivariate Cox regression analysis and identified 6 genes (ATG3, BCL2, CD46, IFNG, NAMPT, TM9SF1) that were independently associated with OS in squamous cell cervical cancer patients." (PMID 33160404, 2020). "After univariate and multivariate Cox regression assay of differentially expressed ARGs, 6 ARG (ATG3, BCL2, CD46, IFNG, NAMPT, TM9SF1) related prognostic signatures for squamous cell cervical cancer were constructed." (PMID 33160404, 2020).
Stargardt disease (1 paper, 2023). "In addition to what has been mentioned, in Stargardt disease, lipofuscin-accumulated RPE cells display increased activity of C3 complement, and as there is a negative correlation between C3 and CD46 levels, the inhibition of the complement cascade decreases." (PMID 37600916, 2023).
subacute sclerosing panencephalitis (1 paper, 2021). A chronic progressive encephalitis that develops a few years after measles infection and presents with a demyelination of the cerebral cortex. "Human CD46 is down-regulated in the postmortem brain of Measles virus-induced subacute sclerosing panencephalitis subjects." (PMID 34408631, 2021).
thalassemia intermedia (1 paper, 2020). "Resulting Hbbth3 CD46+/+ mice have the typical phenotype of thalassemia intermedia." (PMID 32814708, 2020).
tuberculosis (1 paper, 2023). A chronic, recurrent infection caused by the bacterium Mycobacterium tuberculosis. "However, little is known about the value of complement regulatory protein (CD46, CD55, and CD59) in the differential diagnosis of tuberculosis." (PMID 36820087, 2023).
tumor (153 papers, 1993 to 2026). "In another study conducted on renal tumor cells, a low expression level of CD46 was associated with less advanced tumor growth." (PMID 41526546, 2026). "For instance, one study reported that increased expression of the complement system-related protein CD46 was linked to enhanced invasive characteristics of BLCA tumor cells, while another study pointed to the protective effects of this system in BLCA." (PMID 40283026, 2025). "Particularly, the expression level of CD46 was found to be significantly associated with tumor stage." (PMID 34572075, 2021). "The augmented expression of CD55 and CD59 suggested a predominant role in progression of ccRCC, whereas the amount of CD46 was significantly associated to tumour stage." (PMID 34572075, 2021). "In this regard, intratumoral and IV therapies that utilize the nonpathogenic oncolytic measles virus Emonston strain (MV-Edm) showed significant inhibition of tumor growth, survival benefits, and tumor regression in susceptible mice via CD46 targeting." (PMID 33718121, 2020). "Injection of Ad5/35-tk/GCV caused much greater tumor-suppression in mice bearing CD46-overexpressed cancer xenograft compared to mock group." (PMID 27203670, 2016). "The association between CD46 expression and clinical parameters in tumor microenvironment." (PMID 38919630, 2024). "In ovarian cancer for example, CD46 expression was linked to shorter revival-free time, defined as the time from the primary surgical treatment until the time of diagnosis of a recurrent tumor or death, and an overall less favorable outcome." (PMID 31164885, 2019). "In addition, we found that CD46 signaling network was strengthened in the low-risk group, which suggested that it may play an important role in the process of inhibiting tumor progression." (PMID 36189258, 2022). "(a) The need continues for enhancing therapeutic effectiveness by decreasing the potential for provoked immune responses (preexisting antibodies) as well as improving patient stratification to address tumor heterogeneity of CD46 expression." (PMID 40309774, 2025). "The therapeutic followed a path of development in which a phage-isolated scFv, called UA20, was used to capture a tumor antigen identified as CD46 via mass spectrometry." (PMID 40309774, 2025). "Like Adstiladrin, this study also uses an adenoviral vector, but it targets cancer stem cells and has been modified with a type 35 adenovirus fiber that binds to CD46, which is expressed by most tumor cells as well as CAR." (PMID 40011711, 2025). "For related research, the CD46 shRNA interference test, immunohistochemistry (IHC), flow cytometry, qRT-PCR detection, Western blot, and tumor-bearing animal models were used." (PMID 40475017, 2025). "Measles Virus (MeV) is a negative-sense ribonucleic acid (RNA) virus that is oncotropic for CD46 expression on tumor cells." (PMID 41228258, 2025). "The CD150 receptor is often highly expressed in hematologic malignancies, while CD46 expression is common and elevated in many tumor types, thus providing MeV with a natural tendency to infect cancer cells." (PMID 41294877, 2025). "For example, tumor cells with high CD46 density were preferentially killed relative to lower expressing nontransformed cells by the oncolytic agent, MV-Edm." (PMID 40309774, 2025). "Interfering with CD46 can up-regulate the expression of autophagy apoptosis genes, reduce the tumor inflammatory microenvironment, induce the apoptosis of OSCC cells, and inhibit the proliferation and metastasis of OSCC." (PMID 40475017, 2025). "MeV also uses signaling lymphocyte activation molecule (CD150/SLAM) and Nectin-4 as receptors, but CD46 is the most commonly overly expressed receptor on tumor cells." (PMID 41228258, 2025). "The CD46-targeted AdV chimera demonstrated significantly reduced tumor growth in both bladder and colorectal cancer models." (PMID 40309774, 2025).
tumor (continued). "This indicates that CD46 can promote tumor proliferation and escape by inhibiting the activation of autophagy apoptotic genes." (PMID 40475017, 2025). "It is also important to note that there can be variability in CD46 expression even among similar tumor types." (PMID 40309774, 2025). "In vivo experiments showed that the tumor volume of the shRNA group was significantly smaller than that of the SC-shRNA group (P<0.01), the expression of CD46 and TREM1 was decreased considerably, and the expression of LC3B and ATG5 was higher (P<0.01)." (PMID 40475017, 2025). "CD46 also is becoming recognized as a potential tumor target or prognostic indicator because complement (and CD46) expression is often dysregulated (i.e., increased) during tumorigenesis." (PMID 40309774, 2025). "Challenges include the possibility of preexisting neutralizing antibodies, the likely necessity for the tumor to overexpress CD46, and potential difficulty of manufacturing such agents." (PMID 40309774, 2025). "This design enables the virus to enter cells expressing human CD46, which is widely expressed in tumor cells." (PMID 39271928, 2024). "Subsequently, CD46 expression changes within the tumor were assayed following radiopharmaceutical treatment." (PMID 38389832, 2024). "The measles virus vaccine strain typically acts by binding to the cell surface receptor CD46, which is often upregulated in many tumor cells." (PMID 39342391, 2024). "On the other hand, the part of CDC in killing tumor cells in vivo is less clear, particularly for solid tumors, in part because tumor cells themselves express membrane-bound complement regulators (CD46, CD55, and CD59)." (PMID 38085594, 2024). "Mandatory for infection using LOAd viruses is that the tumour cells express the viral entry receptor CD46." (PMID 38494863, 2024). "Tumor cells often express higher levels of CD46 compared to healthy cells, which enhances MV’s specificity for tumors." (PMID 39697335, 2024). "The Ad5/Ad34 chimeric fiber of ICVB-1042 is designed to enable cell entry via human CD46 (huCD46), a surface protein widely expressed in tumor cells." (PMID 39271928, 2024). "We further developed a novel human monoclonal antibody YS5 that binds to a tumor selective epitope on CD46 and generated an antibody–drug conjugate (ADC) by conjugating auristatin derivatives to YS5." (PMID 36906664, 2023). "Since in vivo studies with patient-derived xenografts are the gold standard for determining tumor-initiating cell potential, we studied the effect of CD46–ADC in those models." (PMID 38001595, 2023). "Measles does preferentially infect tumor cells since CD46, as another surface receptor, is up-regulated in tumors and a certain threshold of expression is required for entry." (PMID 37040283, 2023). "One of these, YS5, binds to a tumor selective conformational epitope, enabling therapeutic targeting of CD46." (PMID 37760506, 2023). "The increased expression of CD46 on tumor cells suggests the emergence of a mechanism to protect cancer cells from the body's immune response." (PMID 37621847, 2023). "CD46-targeted radionuclide therapy has shown promising results in preclinical studies, with significant tumor growth inhibition observed in various tumor models." (PMID 39380959, 2023). "Tumor cells can be characterized by the expression of specific proteins, such as CD46 molecules, and their invasive growth is facilitated by tumor-specific proteases." (PMID 36366531, 2022). "In contrast, CD46, the cellular receptor for Ad35, is markedly upregulated in numerous types of malignant tumor cells, such as HCC cells." (PMID 36146619, 2022). "In tumour cells, CD46 can block the immune function mediated by the complement system and contribute to immune escape." (PMID 35692800, 2022). "Owing to the upregulation of CD46 on many malignant tumors, researchers replaced Ad5 fiber with the fiber of serotypes 11/35 to target tumor cells." (PMID 36311790, 2022).
tumor (continued). "Next, we tested the growth of B16-CD46 cells in vivo and analyzed the expression of CD46 in tumor biopsies 17 days after tumor injection." (PMID 35141399, 2022). "MV-CD46-muPA, a dual-targeted oncolytic MV that simultaneously targets murine stromal (via uPAR) and human cancer cells (via CD46), markedly enhances antitumour effects on the HT-29 tumour model compared to CD46-targeted MV alone." (PMID 35303878, 2022). "Edmonston strain of measles virus (MV-Edm) selectively targets tumor cells through CD46, which is known to be overexpressed in many human malignancies." (PMID 35284629, 2022). "A major concern is the presence on tumor cells of inhibitory membrane-bound complement regulatory proteins (mCRPs) such as CD46, CD55, and CD59, which enable cancer cells to evade complement attack." (PMID 35052426, 2021). "Hypoxic tumor cells have upregulated expression of C3-C3a-C3aR axis and downregulated CD55, CD46, and FH, which play important roles in tumor cell proliferation and CSCs stemness maintenance." (PMID 33869223, 2021). "For instance, HSV uses CD46, a membrane cofactor protein involved in cell fusion, as a receptor to enter cells, and this factor is overexpressed in tumor cells, including MM cells." (PMID 34960727, 2021). "We have previously established that cell lysis induced by MeV glycoproteins occurred only above a certain CD46 surface expression threshold, confirming the tumor selectivity of the virus." (PMID 33534834, 2021). "Then, by sophisticated proteomic approaches, the authors investigated the internalizing pathway of anti-CD46 antibodies and identified a mechanism of tumor-selective entry via micropinocytosis, leading to outstanding selective killing of cancer cells." (PMID 34572075, 2021). "Further genetic analysis revealed that the major capsid proteins of this chimeric vector were derived from Ad11, attaching to CD46 that is widely expressed on tumor cell surfaces." (PMID 32370135, 2020). "CD46 molecule being a receptor for attenuated strains of MV is known to be upregulated on the surface of tumor cells." (PMID 32033013, 2020). "CD46 RNA expression levels in the tumor tissues from the 12 patients had a weak correlation with the number of viral genomes in the patients' blood on day 4 (Spearman's rank correlation, R = .1287; P = .6865)." (PMID 31944306, 2020). "It was reported that MV infection induced cell death of several cancer cell lines other than MM cells, and that its efficacy was correlated to the level of CD46 expression by tumor cells." (PMID 32653014, 2020). "Ad11 and Ad35 belong to the subtype B group and use CD46 as their cellular receptor, which is widely expressed on diverse tumor cell types." (PMID 32370135, 2020). "Complement components that were most frequently upregulated in tumor tissues were CD46, C2 and complement factor B (CFB)." (PMID 33628739, 2020). "Two studies demonstrate that efficiency of cellular virus entry into and killing of tumor cells correlates with CD46 cell surface protein expression." (PMID 33291506, 2020). "Complement deposition also is frequently noted in tumor tissue and soluble activation fragments are identified in patients’ sera, including increased levels of soluble CD46." (PMID 33147799, 2020). "Expression of CD46 is increased in tumour cells, and more efficient uptake in the brain was observed for a chimeric Ad5/11F vector." (PMID 30956777, 2019). "CD46 activation on γδ T-cells has also been shown to directly suppress their IFNγ and TNFα production, which can further lead to a pro-tumor environment." (PMID 31164885, 2019). "Because of the great deal of data showing that CD46, CD55, and CD59 expression are linked to worse clinical outcomes, and are in some cases highly specific for tumor cells, many approaches to block mCRP expression on tumor cells have been studied." (PMID 31164885, 2019).